G6PD (glucose-6-phosphate dehydrogenase)
Diseases named in the same sentence as G6PD in open-access papers (continued):
Sharing a sentence is not in itself a finding about the gene and the disease.
dengue (13 papers, 2008 to 2026). "This study aimed to characterize the spectrum of G6PD mutations and explore trends in hemoglobin levels among adult dengue patients in Thailand." (PMID 40966243, 2025). "This study aimed to characterize the spectrum of G6PD mutations in adult dengue patients in Thailand and to explore differences in hemoglobin level dynamics across dengue phases in individuals with and without G6PD mutations." (PMID 40966243, 2025). "In summary, this study provides detailed molecular and functional characterization of G6PD variants in Thai dengue patients and sheds light on the interaction between host genetic factors and infection-induced oxidative stress." (PMID 40966243, 2025). "Two in vitro studies demonstrated that human monocytes from G6PD-deficient individuals had higher replication of dengue virus serotype 2, and these studies suggested that the likelihood of severe dengue was likely to increase in G6PD-deficient individuals." (PMID 30601843, 2019). "Real-time PCR for three known single nucleotide polymorphisms (SNPs) in the G6PD gene in Myanmar, Mahidol, Kaiping and Mediterranean, was performed in 128 of 196 dengue-confirmed samples (64 males and 64 females)." (PMID 30601843, 2019). "Well-designed studies are needed to demonstrate that G6PD-deficient individuals are at risk of severe dengue." (PMID 24625456, 2014). "Glucose-6-phosphate dehydrogenase (G6PD) deficiency is prevalent in Southeast Asian countries where dengue is also endemic." (PMID 24625456, 2014). "This conclusion also supports the public health implication that more efficient prevention and control of dengue is required in areas in which many G6PD-deficient patients live." (PMID 18270558, 2008). "In the context of dengue, oxidative stress and altered redox balance in G6PD-deficient cells may promote viral replication and impair immune cell function, making them more vulnerable." (PMID 40966243, 2025). "Routine G6PD screening and continuous hemoglobin monitoring may help identify individuals at risk of hemoglobin decline and guide supportive care strategies in dengue-endemic regions." (PMID 40966243, 2025). "Changes in hemoglobin levels during dengue phases, stratified by G6PD variant." (PMID 40966243, 2025). "This pattern supports the hypothesis that oxidative stress in dengue may trigger subclinical or overt hemolysis in G6PD-deficient patients, consistent with previous findings in children." (PMID 40966243, 2025). "Glucose-6-phosphate dehydrogenase (G6PD) deficiency may affect the clinical presentation of dengue due to the altered redox state in immune cells." (PMID 30601843, 2019). "Since the outcome of these studies is inconclusive, well-designed studies are needed to demonstrate whether G6PD-deficient individuals are at risk of severe dengue with statistical significance." (PMID 24625456, 2014). "We suggest that redox imbalance observed in infected monocytes from G6PD-deficient individuals may facilitate dengue transmission and affect clinical outcome." (PMID 24625456, 2014). "However, this study is based on only a modest number of hospitalized patients and therefore provides little information on the incidence of severe dengue in G6PD deficient individuals." (PMID 24625456, 2014). "Higher viral loads in G6PD-deficient individuals may increase the probability of dengue transmission to others via infected mosquitos." (PMID 24625456, 2014). "In this study, we screened for G6PD gene mutations in a series of G6PD-deficient adult males who were working with insecticides (organophosphorus and carbamate) in dengue prevention and in a group of unrelated male children suspected of having erythroenzymopathy." (PMID 21637675, 2009). "Severe dengue was diagnosed in 5/29 (17.2%) children with < 60% enzyme activity and in 46/167 (28%) children with G6PD levels > 60% (p = 0.249)." (PMID 30601843, 2019).
dengue (continued). "High prevalence of G6PD is also reported in African population but a low incidence of severe dengue is noted in populations of African origin in a couple of studies conducted in Cuba and Haiti." (PMID 24625456, 2014). "Such hemolysis can counteract the typical hemoconcentration seen in dengue, which explains why patients with G6PD deficiency did not exhibit the marked hemoconcentration observed in non–G6PD-deficient groups." (PMID 40966243, 2025). "Among the 111 individuals (48.1%) carrying G6PD mutations, it was found that these mutations were associated with changes in hemoglobin levels during the course of dengue illness compared to those without mutations." (PMID 40966243, 2025). "Reference values for G6PD activity among confirmed dengue paediatric patients." (PMID 30601843, 2019). "Whether G6PD genotypes other than Mahidol could affect dengue severity cannot be excluded based on our current study." (PMID 30601843, 2019). "Prevalence of G6PD among confirmed dengue paediatric patients according to WHO classification." (PMID 30601843, 2019). "G6PD genotyping in paediatric patients with confirmed dengue." (PMID 30601843, 2019). "Malaria infection, dengue fever and typhoid fever are prevalent in Lao PDR and knowing the G6PD status in local health areas, especially Lao Theung group, helps improve the management of acute haemolysis related to these infections." (PMID 33413378, 2021). "Out of 212 enrolled patients, 16 were excluded (2 did not have sufficient blood volume, 11 had a negative dengue result, and 3 lacked quantitative G6PD results)." (PMID 30601843, 2019). "In addition, 6/25 (24%) study participants had a G6PD SNP, and 25/103 (24%) did not have a detectable SNP and severe dengue (p = 0.977)." (PMID 30601843, 2019). "G6PD status related to severe and non-severe dengue among confirmed dengue paediatric patients." (PMID 30601843, 2019).
type 2 diabetes (13 papers, 2005 to 2025). "We next explored the implications of XCI at G6PD, another chromosome X gene associated with type 2 diabetes." (PMID 41286645, 2025). "Hypoactive or hyperactive G6PD has been linked to type II diabetes pathology." (PMID 39621725, 2024). "We explored the implications of XCI with respect to DUSP9 and G6PD in the context of type 2 diabetes." (PMID 41286645, 2025). "In a type-2 diabetes model, increased levels of cytokines TNF-α, IL-6, and IL-1β were linked to decreased G6PD activity due to NF-κB activation and endoplasmic reticulum stress." (PMID 39726786, 2024). "G6PD activity can be taken as a biomarker of oxidative stress and poor glycemic control in type 2 diabetic patients." (PMID 26317017, 2013). "In peripheral blood, G6PD was mostly silenced, and both individuals in whom G6PD escaped XCI were type 2 diabetes controls." (PMID 41286645, 2025).
acute myeloid leukemia (12 papers, 2012 to 2025). Acute myeloid leukemia (AML) is a group of neoplasms arising from precursor cells committed to the myeloid cell-line differentiation. "At the same time, G6PD overexpression was found to be associated with an increase in mTORC1 activity in blood tumors such as acute myeloid leukemia, and also predicts a poor prognosis." (PMID 35938165, 2022). "Fialkow and colleagues studied X-chromosome inactivation pattern of hematopoeisis in 27 patients with acute nonlymphocytic leukemia who were heterozygous for the X-chromosome-linked enzyme G6PD." (PMID 23150832, 2012). "This is in agreement with a previous study on acute myeloid leukemia on the interplay between G6PD inhibition and mTORC1 activity, since mTOR is a conserved serine/threonine kinase controlling cell growth and metabolism in response to nutrients, growth factors, cellular energy, and stress." (PMID 36271440, 2022). "Knockdown of G6PD reduces NADPH level in acute myeloid leukaemia (AML) cell lines." (PMID 27586085, 2016). "Moreover, G6PD has been pinpointed as a new biomarker in acute myeloid leukemia (AML), and its overexpression positively correlated with poor prognosis of AML patients." (PMID 33041664, 2020). "Similarly, the up-regulation of glucose-6-phosphate dehydrogenase (G6PD), a pivotal enzyme in NADPH production and cell redox balance, enhanced glycolysis activation in acute myeloid leukemia cells." (PMID 36673351, 2023). "This is not the case in rodents, and IDH1mt does not increase the survival of acute myeloid leukemia patients because glucose-6-phosphate dehydrogenase (G6PD) is the major provider of NADPH in white blood cells rather than IDH1." (PMID 33810170, 2021). "In acute myeloid leukemia (AML) cell models, SIRT2 promoted the Warburg effect by deacetylating and activating glucose-6-phosphate dehydrogenase (G6PD) enzyme, increasing the production of NADPH, and supporting the biosynthesis of macromolecules that are essential for rapid cell proliferation." (PMID 32117717, 2020).
renal cell carcinoma (12 papers, 2015 to 2026). "have found that G6PD facilitates renal cell carcinoma proliferation through a positive feedback loop involving the activation of the G6PD/ROS/p−STAT3/Cyclin D1 axis." (PMID 37601657, 2023). "IL-6 has previously been shown to be the second most altered gene in HS5 cells as compared to HS27a and has been found to drive G6PD expression in renal cell carcinoma." (PMID 35213227, 2022). "G6PD is highly expressed in renal cell carcinoma, and high expression affects the cell cycle." (PMID 37853322, 2023). "Our previous study indicated that G6PD is overexpressed in clear cell renal cell carcinoma (ccRCC), the most common subtype of RCC." (PMID 29312589, 2017). "In addition, G6PD can also be upregulated via epigenetic perturbation (histone demethylase gene KDM5C depletion), which increases the flux of PPP to enhance NADPH and GSH synthesis to promote ferroptosis resistance in renal cell carcinoma (RCC)." (PMID 39061847, 2024). "Based on the KEGG analysis, G6PD was enriched in central carbon metabolism in cancer, and HRAS and NRAS could be involved in many signaling pathways, such as AGE-RAGE signaling pathway in diabetic complications, human cytomegalovirus infection and renal cell carcinoma." (PMID 37143953, 2023).
cerebral malaria (11 papers, 2014 to 2022). A sequestration of Plasmodium falciparum in the brain, which can cause coma and/or seizures. "Evidence largely gathered from Africa indicates that G6PD deficiency protects against cerebral malaria and against high parasitaemias, but relatively few data are available for Asia." (PMID 28356147, 2017). "G6PD+202T was associated with an increased risk of severe malarial anaemia (odds ratio [OR] = 1.18, p = 7.5x10−5) and a decreased risk of cerebral malaria (OR = 0.91, p = 7.2x10−3) in males and females combined under an additive genetic model." (PMID 28067620, 2017). "Evidence from large case control studies indicates that G6PD deficiency protects against cerebral malaria and against high parasitaemias." (PMID 28356147, 2017). "This raises the possibility that the protection afforded by G6PD deficiency against cerebral malaria might depend on genetic background or operate through some mechanism other than parasite survival inside the enzyme-deficient red cell." (PMID 26738565, 2016). "As long as the proportion of cerebral malaria cases remains greater than approximately 27%, the frequency of G6PD+202T increases over time to an equilibrium value, otherwise it decreases steadily and will be eliminated (dotted black line on red background)." (PMID 28067620, 2017). "If individuals carrying G6PD+202T are excluded, the mean G6PDd score was 6% in controls, 5.6% in cerebral malaria cases and 7.1% in severe malarial anaemia cases." (PMID 28067620, 2017). "The inhibition of G6PD and NO overproduction induced by RRx-001 suggested its application in cerebral malaria (CM)." (PMID 26017006, 2015). "As expected G6PD+202T showed strong evidence of heterogeneity of effect on different sub-phenotypes, with more than 90% of the posterior weight resting on models indicating different effects on cerebral malaria and severe malarial anaemia." (PMID 28067620, 2017). "We analyzed the pathological progression of experimental cerebral malaria (ECM) and acute liver injury in mice with different G6pd activity infected with P.berghei." (PMID 34456927, 2021). "That we do not observe a protective effect of G6PD deficiency heterozygosity on pneumococcal disease risk may suggest that G6PD deficiency alleles do indeed confer specific protection against cerebral malaria, but may equally represent a lack of study power to detect such an effect." (PMID 32536341, 2020).
lung adenocarcinoma (11 papers, 2017 to 2026). A carcinoma that arises from the lung and is characterized by the presence of malignant glandular epithelial cells. "Our previous research has revealed a significant correlation between G6PD and the poor prognosis of lung adenocarcinoma patients." (PMID 39138186, 2024). "However, the specific mechanism by which METTL14 regulates glucose-6-phosphate dehydrogenase (G6PD) to promote the progression of lung adenocarcinoma (LUAD) is not well understood." (PMID 39138186, 2024). "Besides, G6PD was significantly upregulated in lung adenocarcinoma (LUAD) cell lines and promoted proliferation and migration in vivo." (PMID 37601657, 2023). "Previous studies have shown that G6PD is an independent prognostic factor for lung adenocarcinoma." (PMID 34630529, 2021). "G6PD (glucose-6-phosphate dehydrogenase) is involved in the pentose phosphate pathway of energy metabolism and has been verified to prevent erastin-induced ferroptosis in human lung adenocarcinoma cells while it was knocked down by the corresponding shRNA." (PMID 34222241, 2021). "NRF2-regulated PPP genes, including G6PD, PGD, TKT, and TALDO1 were first identified in lung adenocarcinoma A549 cells." (PMID 33859744, 2021). "In fact, upregulation of both oxidative and non-oxidative PPP enzymes, including G6PD, 6PGD, TALDO, and TKT was demonstrated to drive metabolic reprogramming and NRF2-dependent proliferation in lung adenocarcinoma cells (A549)." (PMID 28553614, 2017).
non-small cell lung carcinoma (11 papers, 2017 to 2024). A group of at least three distinct histological types of lung cancer, including non-small cell squamous cell carcinoma, adenocarcinoma, and large cell carcinoma. "G6PD, a key molecule involved in pentose phosphate pathway, has been reported to be involved in erastin-induced ferroptosis in non-small cell lung cancer cells." (PMID 37671041, 2023). "G6PD was reported to inhibit erastin-induced ferroptosis when knocked down in non-small-cell lung cancer cells by reducing ROS directly under the pentose phosphate pathway." (PMID 36313179, 2022). "In this study, disordered metabolism in non-small cell lung cancer was demonstrated by increased G6PD and SDHA protein levels via immunofluorescence, and up-regulated lactate dehydrogenase was found to be associated with poor prognosis." (PMID 34150616, 2021). "G6PD, which is involved in the pentose phosphate pathway, has been reported to prevent erastin-induced ferroptosis when it was knocked down in non-small cell lung cancer cells." (PMID 32760210, 2020). "In terms of energy metabolism, G6PD and PGD, associated with the pentose phosphate pathway, can prevent erastin-induced ferroptosis when it is knocked down in non-small cell lung cancer cells." (PMID 33330074, 2020). "SNHG14 participates in the cell proliferation, invasion and migration of non-small cell lung cancer cells by regulating miR-206/G6PD." (PMID 32912324, 2020). "For instance, within non-small cell lung cancer (NSCLC), a number of genes intricately connected to glycolytic metabolism, including HK-1, G6PD, PKM, SDH, IDH, and HIF-1a, exhibit noteworthy elevations in histone lactylation levels." (PMID 38481814, 2024). "In the non-small cell lung cancer model the following 5 DEPs were found to be involved in the GSH metabolism pathway (G6PD, PRDX2, IDH1, MGST1 and 6PGD), 4 DEPs in the PPP pathway (G6PD, TALDO1, TKT and 6PGD) and 1 DEP involved in the glycolysis pathway (ALDH3A1)." (PMID 28303926, 2017).
hereditary spherocytosis (10 papers, 2013 to 2025). Hereditary spherocytosis is a congenital hemolytic anemia with a wide clinical spectrum (from symptom-free carriers to severe hemolysis) characterized by anemia, variable jaundice, splenomegaly and cholelithiasis. "Membrane defects include hereditary spherocytosis and elliptocytosis, and the group of hereditary stomatocytosis; glucose-6-phosphate dehydrogenase and pyruvate kinase, are the most common enzyme deficiencies." (PMID 34627331, 2021). "Of the patients included in the study, all patients with haemolytic disease were caused by blood group incompatibility, and there were no cases of G6PD or spherocytosis." (PMID 40745041, 2025). "Investigation for common causes of hemolytic anemia was negative (peripheral blood smear was normal, and he had a negative Coombs test, normal G6PD, and normal flow cytometry spherocytosis)." (PMID 40277844, 2025). "There were at least five representative cases for all disorders, with the exception of spherocytosis and hemoglobin D. A linear regression between the STANDARD G6PD Test results and the reference assay showed a high degree of correlation, with an R-squared value of 0.90." (PMID 34543346, 2021).
iron deficiency (10 papers, 2009 to 2026). "Thus, the increase of the G-6-PD activity can also be one of defense mechanisms against oxidative stress caused by iron deficiency, and as a consequence, it can cause the increase in pentose levels." (PMID 37101600, 2023). "Hence we aimed to investigate the relationship between iron deficiency and glucose-6-phosphate dehydrogenase, 6-phosphogluconate dehydrogenase and glutathion reductase enzyme activities in patients with IDA." (PMID 25097522, 2014). "Glucose-6-phosphate dehydrogenase (G6PD) levels and iron studies were within normal limits, excluding enzymopathy and iron deficiency." (PMID 42291950, 2026).
multiple myeloma (10 papers, 2012 to 2026). "PDIA3P has been found to regulate multiple myeloma cell growth and resistance to the drug bortezomib through its influence on the enzyme glucose 6-phosphate dehydrogenase (G6PD) and the pentose phosphate pathway." (PMID 41362671, 2026). "They found that PDIA3P regulates multiple myeloma growth and drug resistance through glucose 6-phosphate dehydrogenase (G6PD) and the pentose phosphate pathway (PPP)." (PMID 33652661, 2021). "Of two studies meeting the search criteria for myeloma, both showed statistically significant G6PD overexpression in MM samples." (PMID 22848499, 2012). "LncRNA-PDIA3P by interacting with c-Myc through G6PD/PPP pathway could regulate cell proliferation multiple myeloma." (PMID 33123468, 2020). "The study has uncovered a novel regulatory mechanism in multiple myeloma, where the lncRNA PDIA3P interacts with the c-Myc oncogene to modulate its transcriptional activity, thereby regulating the expression of the downstream gene G6PD and influencing flux through the pentose phosphate pathway." (PMID 41362671, 2026). "Glucose-6-phosphate dehydrogenase (G6PD) as the rate-limiting enzyme in the pentose phosphate pathway (PPP) is well-established as an aberrantly expressed protein in numerous clinical diseases; however, its role in cancer, specifically in multiple myeloma (MM) remains elusive." (PMID 36271440, 2022).
renal failure (10 papers, 2012 to 2026). "Due to her renal insufficiency, she was started on dapsone for pneumocystis jirovecii pneumonia prophylaxis after confirmation of normal glucose-6-phosphate dehydrogenase (G6PD) activity level by quantitative testing twice." (PMID 25628986, 2015).